LACTB (lactamase beta)
Diseases named in the same sentence as LACTB in open-access papers (continued):
Sharing a sentence is not in itself a finding about the gene and the disease.
osteosarcoma (4 papers, 2023 to 2025). A usually aggressive malignant bone-forming mesenchymal neoplasm, predominantly affecting adolescents and young adults. "Further studies indicated that approximately 92.31% of osteosarcoma patients with high LACTB expression level exhibit two mutations, M5L and R469K, in the protein." (PMID 39941048, 2025). "Two missense mutations (rs34317102 and rs2729835) exist simultaneously in 92.31% of osteosarcoma patients and cause M5L and R469K double mutations in LACTB, suggesting the biologic function of LACTB protein may be altered in osteosarcoma." (PMID 39324579, 2024). "In addition, another research group reported that in methotrexate (MTX)-resistant osteosarcoma cells, LACTB expression is relatively reduced, suggesting that downregulation of LACTB may be associated with chemoresistance in osteosarcoma." (PMID 39941048, 2025). "Detection of LACTB expression in osteosarcoma cells revealed that LACTB is highly expressed in these cells, and its elevated levels are generally associated with poor prognosis." (PMID 39941048, 2025). "We found that the previously reported tumor suppressor proteins LACTB, c‐Myc, and Mcl‐1 were highly expressive in osteosarcoma and with a robust inverse correlation to patient survival outcomes." (PMID 40616392, 2025). "Based on that, combined with MTX-resistant mRNA and miRNA data, we established a new 4-gene prognostic signature for osteosarcoma, including two high-risk MTXDEGs (CPE, PDK1) and two low-risk MTXDEGs (LASP1, LACTB)." (PMID 37937197, 2023). "The expression of carcinogenic proteins LACTB, c‐Myc, and Mcl‐1 related RNA in the osteosarcoma U2OS cell line detected by qRT‐PCR could be inhibited by Mifepristone intervention." (PMID 40616392, 2025). "However, preliminary study reveals that LACTB is overexpressed in osteosarcoma and indicates poor prognosis." (PMID 39324579, 2024).
ovarian carcinoma (4 papers, 2023 to 2025). A malignant neoplasm originating from the surface ovarian epithelium. "Additionally, the expression level of LACTB is positively correlated with overall survival in ovarian cancer patients, with higher LACTB expression associated with longer survival times and improved prognosis." (PMID 39941048, 2025). "In ovarian cancer, overexpressed LACTB drives cancer cells to accumulate in the G1 phase, thereby promoting apoptosis." (PMID 39941048, 2025). "Research indicates that LACTB expression is significantly reduced in ovarian cancer tissues compared to normal ovarian tissues." (PMID 39941048, 2025). "We show that expression of LACTB leads to inhibition of ovarian cancer cell growth in vivo and in vitro, decreases cancer stemness properties and migration, and increases ovary cancer cell differentiation." (PMID 36375842, 2023). "This study uncovers a novel role of LACTB in ovarian cancer and proposes new ways of counteracting the oncogenic EMT program in this model system." (PMID 36375842, 2023). "As such, this study shows for the first time the tumor suppressive role of LACTB in ovarian cancers and the importance of Slug EMT transcription factor in its mechanism." (PMID 36375842, 2023). "We show that re-expression of LACTB in ovarian cancer negatively affects the growth of different ovarian cell lines in vitro and in vivo." (PMID 36375842, 2023). "Considering the strong tumor suppressive activity of LACTB in cancers of epithelial origin, we decided to investigate the role of LACTB in epithelial ovarian cancer." (PMID 36375842, 2023). "To further understand the role of LACTB in ovarian cancer, we re-introduced a doxycycline-inducible LACTB to ovarian cancer cell lines, which had the endogenous LACTB down-regulated." (PMID 36375842, 2023). "The mechanism responsible for this tumor suppressive effect is the LACTB-induced inhibition of the EMT program in ovarian cancer cells, which happens through LACTB-dependent down-regulation of Slug EMT transcription factor." (PMID 36375842, 2023). "Our study showed that LACTB is significantly down-regulated in ovarian cancer cells and in human ovarian cancer tissues." (PMID 36375842, 2023). "To elucidate how LACTB is clinically relevant to patients with ovarian cancer, we further analyzed the prognostic value of LACTB expression in patients with ovarian cancer." (PMID 36375842, 2023). "In our study, we uncovered the importance of Slug in LACTB’s tumor suppressive mechanism in ovarian cancers." (PMID 36375842, 2023). "In summary, our study points to the possibility that the activation of the tumor suppressor LACTB pathway is one of the options for inhibiting EMT program in ovarian cancers via the inhibition of the Slug expression." (PMID 36375842, 2023). "On the other hand, cells where LACTB was expressed had diminished ability to migrate compared with control cells, showing the ability of LACTB to counteract ovarian cancer cell migratory properties." (PMID 36375842, 2023). "Overall, these results showed that induction of LACTB in ovarian cancer cells leads to decrease in cancer stem cells properties and increase in E-cad." (PMID 36375842, 2023). "We show the ability of LACTB to function as a tumor suppressor in ovarian cancer through down-regulation of Slug and induction of differentiation." (PMID 36375842, 2023). "To map the genetic programs influenced by the expression of LACTB in ovarian cancer, we employed RNA-seq analysis to compare the transcriptomes of non-tumorigenic immortalized cells and PEO4 cells where LACTB was induced for 3 and 6 d." (PMID 36375842, 2023). "We next decided to investigate the expression levels of LACTB in 331 clinically defined human ovarian cancer samples to examine our previous findings in human clinical tissues." (PMID 36375842, 2023).
ovarian carcinoma (continued). "In this study, we show, through in vitro, in vivo, and 3D culture experiments, that the mitochondrial protein LACTB manifests tumor suppressor properties in ovarian cancer." (PMID 36375842, 2023). "Mechanistically, we show that LACTB leads to differentiation of ovarian cancer cells and loss of their stemness properties, which is achieved through the inhibition of the EMT program and the LACTB-dependent down-regulation of Snail2/Slug transcription factor." (PMID 36375842, 2023). "We show that LACTB is significantly down-regulated in epithelial ovarian cancer cells and clinical tissues." (PMID 36375842, 2023). "Aiming to investigate the role of LACTB in epithelial ovarian cancer, we first examined its expression in a cohort of ovarian tumorigenic and non-tumorigenic cell lines." (PMID 36375842, 2023). "Similarly, in ovarian cancer, restoring LACTB expression in cancer cells leads to cell cycle arrest at G1, which suppresses cell proliferation, demonstrating LACTB as a tumor suppressor in this context." (PMID 39941048, 2025). "Notably, re-expression of LACTB has been shown to effectively inhibit the growth of ovarian cancer cells." (PMID 39941048, 2025). "Another possible explanation is that even if there are changes in lipid metabolism in ovarian cancer cells upon LACTB induction, these might be mostly manifested at post-transcriptional levels and therefore not possible to detect by RNA-seq analysis." (PMID 36375842, 2023). "Because both of the cell lines (EFO27 and PEO4) used for the in vivo experiments were derived from metastatic sites, it is reasonable to believe that LACTB re-activation in ovarian cancer metastasis might have a therapeutic effect in counteracting this malignancy." (PMID 36375842, 2023). "Because LACTB was shown previously to exert tumor suppressor properties in cancers of epithelial origin, we focused our attention on analyzing the two types of ovary adenocarcinomas: mucinous and serous, which belong to type I and type II of ovarian cancers, respectively." (PMID 36375842, 2023). "We show that expression of LACTB presents one such option, thus identifying its role as an EMT-inhibiting tumor suppressor in ovarian cancers." (PMID 36375842, 2023). "The immunofluorescence and Western blot analysis showed marked increase in the E-cad expression upon LACTB induction in ovarian cancer cells but not in the non-tumorigenic cells." (PMID 36375842, 2023). "Our results show a robust down-regulation of LACTB in ovarian cancer cells compared with non-tumorigenic cell lines (primary human ovarian cells and fallopian tube cells)." (PMID 36375842, 2023). "To extend these observations to a more physiological 3D culture environment, we investigated the ability of cancer cells to form spheres in the presence or absence of LACTB in a cohort of ovarian cancer and non-tumorigenic cells." (PMID 36375842, 2023). "These experiments confirmed that LACTB’s negative effects on the growth of ovarian cancer cells are mostly realized through down-regulation of the Slug EMT transcription factor." (PMID 36375842, 2023). "The negative effect of LACTB on ovarian cancer cell migration was partially reverted by concomitant Slug over-expression, further confirming the important role of Slug in LACTB tumor suppressive mechanism." (PMID 36375842, 2023). "The results of this experiment demonstrated a significant negative impact of LACTB expression on the stem properties of the tested ovary cancer cell spheres." (PMID 36375842, 2023). "However, our RNA-seq–based study in ovarian cancer background did not reveal any major changes in pathways involved in lipid metabolism upon LACTB induction, and we did not observe down-regulation of PISD protein upon LACTB induction." (PMID 36375842, 2023).
ovarian carcinoma (continued). "To determine whether the down-regulation of LACTB occurs at transcriptional or post-transcriptional level, we performed RT–PCR analysis which showed significant down-regulation of LACTB mRNA levels in all the tested ovarian cancer cell lines compared with the non-tumorigenic cells used as control." (PMID 36375842, 2023).
pancreatic adenocarcinoma (4 papers, 2021 to 2025). "Elevated LACTB expression in tumor tissues is strongly associated with poor prognosis in pancreatic adenocarcinoma patients." (PMID 39941048, 2025). "However, these patients often experience increased treatment challenges and poor prognosis, indicating that the immune infiltration associated with high LACTB expression may promote tumor progression in pancreatic adenocarcinoma." (PMID 39941048, 2025). "In pancreatic adenocarcinoma, LACTB is highly expressed and correlates with elevated levels of cell cycle-related gene." (PMID 39941048, 2025). "In pancreatic adenocarcinoma, patients with elevated LACTB expression generally exhibit greater immune infiltration, as evidenced by positive associations with 28 distinct immune cell types." (PMID 39941048, 2025). "The mRNA and protein expressions of LACTB are high in pancreatic adenocarcinoma;Elevated LACTB mRNA expression in pancreatic adenocarcinoma patients is associated with a poor survival rate." (PMID 36078157, 2022). "This study aimed to find the prognostic value of Beta-lactamase-like (LACTB) in pancreatic adenocarcinoma (PAAD) patients." (PMID 33507917, 2021). "Interestingly, research showed that in contrast to its phenotype in most cancers, LACTB mRNA is significantly upregulated in pancreatic adenocarcinoma tissues." (PMID 39941048, 2025). "Moreover, the immunoreactive score of LACTB protein is markedly higher in pancreatic adenocarcinoma compared to adjacent non-cancerous pancreatic tissue." (PMID 39941048, 2025).
bladder cancer (3 papers, 2024 to 2025). "PCBP1 protects mitochondrial integrity by destabilizing LACTB mRNA, thereby reducing ferroptosis in bladder cancer cells." (PMID 39941048, 2025). "Research investigating LACTB in bladder cancer revealed that poly(C)-binding protein 1 (PCBP1) suppresses LACTB expression by binding to its mRNA and accelerating its degradation in cancer cells." (PMID 39941048, 2025). "Similarly, in bladder cancer, LACTB modulates ferroptosis and mitochondrial function by inducing erastin-mediated ferroptosis, which exacerbates mitochondrial dysfunction and ROS production, counteracting the ferroptosis-inhibitory effects of PCBP1." (PMID 39941048, 2025). "In addition, LACTB has been reported to promote erastin-induced ferroptosis and mitochondrial dysfunction in bladder cancer cells, but it is unclear whether LACTB is an intrinsic trigger of ferroptosis." (PMID 39047638, 2024). "For instance, in bladder cancer, PCBP1 directly promotes LACTB mRNA degradation, thereby regulating its translation and suppressing its tumor-suppressive function." (PMID 39941048, 2025).
lung carcinoma (3 papers, 2022 to 2025). "The study also shows that elevated LACTB expression is strongly associated with improved prognosis in lung cancer patients and effectively suppresses cancer cell migration and invasion." (PMID 39941048, 2025). "Collectively, these findings underscore the critical tumor-suppressive role of LACTB in lung cancer progression." (PMID 39941048, 2025). "Research using data from The Cancer Genome Atlas (TCGA) and Kaplan–Meier Plotter databases indicates that LACTB expression is markedly reduced in lung cancer tissues, accompanied by increased methylation levels on its DNA." (PMID 39941048, 2025). "In addition, in lung cancer, the methylation level of LACTB is elevated though its total expression is decreased, which hints at the importance of PTMs of LACTB and its promotor in cancer research." (PMID 36078157, 2022). "However, the LACTB mutations have been mapped in various cancers, e.g., E121K in BRCA, R371K in lung cancer, and E457K in urinary bladder cancer." (PMID 36078157, 2022). "Moreover, knockdown of LACTB decreases the expression of the epithelial cell-derived markers and increases the expression of stromal cell-derived markers in lung cancer, while overexpressing LACTB inhibits the migration and invasion of H1299 and H1975 cells, suppressing carcinogenesis." (PMID 36078157, 2022). "These notions are supported by previous studies, which showed interconnection of LACTB and EMT also in colorectal and lung cancers." (PMID 36375842, 2023). "For instance, LACTB inhibits cell migration and invasion and suppresses EMT under the administration of docetaxel in lung cancer patients." (PMID 36078157, 2022). "The inconsistency of the LACTB’s roles between lung cancer and NPC may be related to the enzymic properties of LACTB, involving the polymerization dynamics (discussed in Section 3.2) and post-translational modifications (PTMs, discussed in Section 4.3) of LACTB." (PMID 36078157, 2022).
pancreatic cancer (3 papers, 2021 to 2023). "Some of them (ITGA3, CDK1, IFIT3, ANXA1, ANXA2, OAS1, and LACTB) have been studied to varying degrees concerning their relationship with pancreatic cancer." (PMID 36834681, 2023). "LACTB was able to effectively discriminate between normal pancreatic tissue and pancreatic cancer tissue." (PMID 33507917, 2021). "To detect the clinical significance of LACTB expression in PAAD, we analyzed The Cancer Genome Atlas (TCGA) datasets, and the clinical and gene expression data for 183 cases of primary pancreatic cancer were downloaded from the TCGA-PAAD dataset." (PMID 33507917, 2021). "Therefore, 98 primary pancreatic cancer tissues and 69 adjacent noncancerous pancreatic tissues were used to investigate the protein expression level of LACTB by immunohistochemistry (IHC)." (PMID 33507917, 2021).
atherosclerosis (2 papers, 2018 to 2022). A disease characterized by the build-up of fatty material and calcium deposition in the arterial wall resulting in partial or complete occlusion of the arterial lumen. "The miR-125b-5p regulates inflammatory responses and atherosclerosis by targeting LACTB 3′UTR, which directly inhibits LACTB protein and mRNA expression and thereby reduces the expression of monocyte chemotaxis protein-1 (MCP-1)." (PMID 36078157, 2022).
Alzheimer disease (1 paper, 2025). A progressive, neurodegenerative disease characterized by loss of function and death of nerve cells in several areas of the brain leading to loss of cognitive function such as memory and language. "Conversely, increased LACTB expression levels have been reported to be associated with increased risk of Alzheimer's disease in integrative analyses of genome-wide, proteome-wide, and transcriptome-wide association studies." (PMID 40286848, 2025). "LACTB has previously been characterized as a tumor suppressor and as a protein whose increased expression is associated with an increased risk of Alzheimer's disease." (PMID 40286848, 2025). "We used Aβ1–10 as an artificial peptide substrate for LACTB, although it does not seem to be relevant for the pathogenesis of Alzheimer's disease as Aβ is secreted into the extracellular space, whereas LACTB is located in the mitochondrial intermembrane space (IMS)." (PMID 40286848, 2025).
leukemia (1 paper, 2022). A malignant (clonal) hematologic disorder, involving hematopoietic stem cells and characterized by the presence of primitive or atypical myeloid or lymphoid cells in the bone marrow and the blood. "Furthermore, a variety of splice isomers of LACTB have been found in the leukemia cell lines with diverse expression patterns." (PMID 36078157, 2022).
mucinous adenocarcinoma (1 paper, 2023). An invasive adenocarcinoma composed of malignant glandular cells which contain intracytoplasmic mucin. "In our analysis on tissues, LACTB expression was significantly down-regulated in 52% of mucinous adenocarcinomas and 69% of serous adenocarcinomas when compared with LACTB levels in normal ovary epithelial tissues (n = 26)." (PMID 36375842, 2023).
osteonecrosis (1 paper, 2024). A none disease characterized by death of bone tissue due to a lack of blood supply. "Therefore, we speculate that the dysregulation of lipid metabolism induced by corticosteroids in glucocorticoid-induced osteonecrosis of the femoral head leads to upregulation of LACTB expression." (PMID 38384969, 2024).
ovarian tumors (1 paper, 2023). "Induction of LACTB significantly inhibited the growth of ovarian tumors within 2–4 wk of LACTB induction, and the tumors expressing LACTB had smaller weight compared with the control tumors." (PMID 36375842, 2023). "From these experiments, we can conclude that the expression of LACTB in ovarian tumors contributes to the significant reduction of the tumor size and weight under in vivo conditions." (PMID 36375842, 2023).